APOE (apolipoprotein E)
Diseases named in the same sentence as APOE in open-access papers (continued):
Sharing a sentence is not in itself a finding about the gene and the disease.
atherosclerosis (continued). "In the present study, we have tested the prebiotic potency of chitin-glucan, an insoluble dietary fibre, alone or in combination with a pomegranate peel extract (PPE) rich in polyphenols in a model of accelerated atherosclerosis in ApoE−/− mice fed a high fat diet during 8 weeks." (PMID 31578395, 2019). "In contrast, atherosclerosis is unaffected in DT-treated ApoE−/− BDCA2-DTR mice." (PMID 31653058, 2019). "Lack of TGFβ type II receptor signaling in CD11c+ APCs promotes atherosclerosis in ApoE−/− mice." (PMID 31653058, 2019). "Furthermore, in ApoE-/- mice, OSMR deficiency attenuated atherosclerosis development and increased plaque stability." (PMID 31461490, 2019). "Thus, apoE knockout rats were proposed as novel animal model of atherosclerosis promoting also future investigations on intravascular angioplasty and stenting." (PMID 31796798, 2019). "In this study, we evaluated the associations between DNA methylation at ABCG1 (cg06500161 and cg02494239) and APOE (cg14123992) and ischemic stroke and early examinations of atherosclerosis (including cIMT, ABI, and baPWV) in subjects from a family-based study." (PMID 31823830, 2019). "Our results indicated that C8:0 reduced body fat, improved the lipid profiles, suppressed inflammatory cytokine production, downregulated aortic TLR4, MyD88, NF-κB, TNF-α, IKKα, and IKKβ mRNA expression, and alleviated atherosclerosis in the apoE−/− mice (P < 0.05)." (PMID 31182969, 2019). "These factors complicate the relationship between atherosclerosis and AD, and differences in patient selection and whether studies controlled for APOE genotype may go some way towards explaining why results in this area have been mixed." (PMID 31083442, 2019). "Furthermore, in the ApoE−/− model of atherosclerosis, CLA promotes a pro-resolving microenvironment, and we have identified that the monocyte/macrophage is the cellular target through which CLA mediates its effect." (PMID 31139076, 2019). "Whereas ACAT-2 deficiency in mice may restrict synthesis of CE and reduce the accumulation of CE in the plasma lipoproteins and atherosclerosis development in ACAT-2–/–/ApoE–/– mice." (PMID 30696703, 2019). "Furthermore, AMP-dNM treatment was demonstrated to reduce the development of atherosclerosis by lowering plasma cholesterol levels in APOE*3-Leiden and low-density lipoprotein receptor -/- mice." (PMID 31852956, 2019). "Secondly, in the same high-cholesterol (1.25%) diet, ApoE−/− mice had higher plasma cholesterol and more serious pathologic changes, thus minor contributions of genes that potentially result in atherosclerosis might be missed in the prior model." (PMID 31354731, 2019). "Treatment with IL35 reduces atherosclerosis in ApoE−/− mice." (PMID 31653058, 2019). "In order to further investigate the effects associated with CDKN2B-AS1 and ADAM10 on the progression of atherosclerosis in vivo, the ApoE knockout mice recruited for the purposes of the study were placed on a high-fat diet for 10 weeks in order to establish the animal models of atherosclerosis." (PMID 30926762, 2019). "The results suggest that the selected peptides may be involved in the immune response to atherosclerosis, which in the apoE-/- model is accelerated by high fat diet." (PMID 30811493, 2019). "Furthermore, AGE inhibited the vascular inflammation and lipid deposition in progress of atherosclerosis at an early stage in the apolipoprotein E-knockout mice, and AGE also inhibited the development of coronary artery calcification in humans." (PMID 31284512, 2019). "The protective role of APOE in atherosclerosis development was first proven in animal models." (PMID 30851738, 2019). "Trehalose caused a significant decrease of atherosclerotic lesions by almost 40% in the aorta of apoE−/− mice fed a CD as measured by the en face method (11.5 ± 0.9% vs 15.8 ± 1.2%; p < 0.05) and atherosclerosis evaluation at the aortic sinus (40118 ± 3904 μm2 vs 71492 ± 10703 μm2; p < 0.05)." (PMID 30925684, 2019).
atherosclerosis (continued). "ApoE−/− mice act as one of the ideal animal models of hyperlipidemia and atherosclerosis." (PMID 31521120, 2019). "The successful inclusion of atherosclerosis was shown in the ApoE−/− group." (PMID 31886257, 2019). "Furthermore, we determined that systemically delivered viral MIAT shRNA significantly reduced atherosclerosis progression in vivo and promoted plaque stability by enhancing the clearance of apoptotic cells by lesion macrophages in ApoE−/− mice." (PMID 30755588, 2019). "Our observation of Spp1 overexpression in ApoE−/− mouse model indicates that Spp1 may accelerate the process of atherosclerosis by inducing inflammation." (PMID 31446617, 2019). "ApoE deficiency induces severe hyperlipidemia, which is accelerated in animals that are fed an atherogenic/obesogenic high-fat diet (HFD); ApoE deficiency is associated not only with atherosclerosis but also with most features of CMS." (PMID 30818779, 2019). "In the present study, we used IL-12p35-/- mice and ApoE-/- mice to generate ApoE-/- IL-12p35-/- mice to investigate whether the α subunit of IL-35 has effects on atherosclerosis and to explore its potential mechanisms." (PMID 31093011, 2019). "A recent study also showed that absence of serum IgG and IgM reduced atherosclerosis in Prdm1fl/fl Cd19cre/+ ApoE−/− mice, suggesting pathogenic properties of IgGs in atherosclerosis progression." (PMID 31998318, 2019). "Moreover, the inhibitor of DPP-IV sitagliptin also inhibited NF-κB activating AMPK in a model of atherosclerosis in apolipoprotein-E-knockout mice and in rats with streptozotocin-induced diabetes." (PMID 30862093, 2019). "In a diabetic apolipoprotein E-deficient mouse model, decreased levels or lack of GPx-1 accelerates diabetes-associated atherosclerosis." (PMID 31210841, 2019). "Notably, although typical atherosclerosis was observed in the bosentan group, these mice had significantly smaller atherosclerotic plaques than those observed in the ApoE−/− mice." (PMID 31886257, 2019). "Therefore, we set out to investigate the effects of a nutritionally-relevant dose of ESM (0.1% w/w) on gut microbiota composition and atherosclerosis development in apoE−/− mice fed a Western-style diet." (PMID 31117179, 2019). "Rapamycin has the ability to restore impaired autophagy by inhibiting the mammalian target of rapamycin (mTOR), leading to selective clearing of macrophages, increased cholesterol efflux, reduction of apoptotic cells in the plaques, and stabilization of atherosclerosis in ApoE-/- mice." (PMID 31080547, 2019). "Hyperglycemia induces accumulation of HA around vascular smooth muscle cells, increases aortic stiffness and strength, and primes the vascular wall for the deposition of cholesterol, accumulation of leucocytes and accelerated development of atherosclerosis in ApoE−/− mice." (PMID 30678366, 2019). "Thus, we explored the functions of the ARNI LCZ696, compared with the traditional RAS blocker valsartan, on the atherosclerotic plaque and inflammation process in atherosclerosis-prone apoE−/− mice." (PMID 31019233, 2019). "The decreased plasma IL-6 level could, therefore, be partly responsible for the attenuation of atherosclerosis in SP-D/ApoE DKO mice, despite the elevated body weight and plasma lipoproteins, which are known risk factors for the development of CVD." (PMID 31616435, 2019).
atherosclerosis (continued). "Although best recognized for its ability to mediate plasma lipoprotein clearance in the liver and protect against macrophage foam cell formation, our recent understanding of the influence that apoE can exert to control atherosclerosis has significantly widened." (PMID 29789495, 2018). "Specifically, ApoE−/− mouse is a well-established animal model for studying atherosclerosis." (PMID 29922166, 2018). "Consequently, D-PDMP, an inhibitor of glucosylceramide synthase and lactosylceramide synthase, has an astounding protective effect on atherosclerosis development in ApoE−/− mice." (PMID 29892305, 2018). "Furthermore, we confirm the anti-atherogenic effect of active schistosome infection in an ApoE−/− atherosclerosis mouse model and postulate that this protection is due in part to significant reductions in serum ApoC1." (PMID 30483256, 2018). "Like the ε4 allele of the apolipoprotein E gene (APOE), the clusterin gene (CLU) is a risk locus for Alzheimer’s disease, and may play additional roles in atherosclerosis pathogenesis." (PMID 29534716, 2018). "ApoE−/− mice have been widely used as an atherosclerosis animal model." (PMID 30131868, 2018). "We extended these findings and investigated whether inulin may delay or prevent development of atherosclerosis in APOE*3-Leiden (E3L) transgenic mice." (PMID 29401645, 2018). "Moreover, we used ApoE−/− mouse model in the present study since its pathogenesis of atherosclerosis resembles that observed in humans and it has been widely applied in cardiovascular research." (PMID 30533443, 2018). "Notably, TLR4 signaling enhances atherosclerosis development in ApoE−/− mice in an iNKT cell-dependent manner." (PMID 29892305, 2018). "In atherosclerosis other groups have targeted DNA vaccines to vascular endothelial growth factor receptor 2 (VEGFR2), TIE2 (an endothelial marker), and CD99 a leukocyte and endothelial antigen resulting in significantly reduced atherosclerosis and leukocyte infiltration in ApoE-/- mice." (PMID 29641559, 2018). "In order to comprehend the direct effects of alkaloids and to provide further information about the potential translation of the experimental results to humans, we therefore assessed the preventive effect of alkaloids on atherosclerosis in ApoE−/− mice in this systematic review and meta-analysis." (PMID 29922166, 2018). "In apoE-deficient mice, a lack of HO-1 accelerated atherosclerosis, whereas HO-1 induction reduced atherosclerosis in LDL receptor knockout mice and Watanabe heritable hyperlipidemic rabbits." (PMID 30159103, 2018). "Also, miR-1 is found reduced under high fat diet in atherosclerosis prone ApoE knock-out mice, which goes along with enhancement of EC permeability." (PMID 29777114, 2018). "Furthermore, apoE was found to influence levels of cellular miR-146a in monocytes and macrophages to suppress NF-κB–driven inflammation and atherosclerosis in hyperlipidemic mice." (PMID 29789495, 2018). "In addition, Lachnospiraceae and Ruminococcaceae were positively correlated with relative atherosclerosis lesion size in apoE KO." (PMID 30021609, 2018). "Therefore, Western diet-fed apoE KO mice are widely used to study many facets of human hyperlipidemia and atherosclerosis." (PMID 30021609, 2018). "Thus, we developed a novel Treg lineage tracker mouse model; Foxp3-IRES-YFP-Cre-Rosa26-loxp-td-RFP-loxp-ApoE−/− (LT-ApoE−/−) and studied these mice in the context of atherosclerosis." (PMID 29545616, 2018).
atherosclerosis (continued). "Apolipoprotein E-knockout (ApoE KO) mice, which are the most commonly used and well-characterized animal model of atherosclerosis, were treated with a high-fat diet for further plaque development and the monocytes accumulation was continuous and proportional to disease progression." (PMID 29795012, 2018). "Finally, although the ApoE−/− model of atherosclerosis is extensively used due to its development of plaques with similar composition to those of humans, no animal model completely reproduces the human disease." (PMID 30038907, 2018). "Apolipoprotein E- (ApoE-) knockout mice are the most widely used atherosclerosis mouse model." (PMID 29577045, 2018). "In the present study, we investigated the effect of canagliflozin on atherosclerosis formation and demonstrated for the first time, that 5 week canagliflozin administration attenuates atheromatous process in APOE(−/−) mice fed an atherogenic diet for 10 weeks enough for atheroma to be formed." (PMID 30049285, 2018). "Additionally, the results found that ginsenoside Rb1 increased autophagy flux to inhibit apoptosis via cceleration of autophagy via promoting of transformation of LC3 from type I to type II in high-fat diet-induced atherosclerosis in ApoE-/- mice." (PMID 30413028, 2018). "The FH/apoE interaction is hypothesized to limit the progression of atherosclerosis as complement regulation by FH is critical in the prevention self-cell damage and exacerbated inflammation." (PMID 30519244, 2018). "ApoE−/− mice accumulate in their plasma large quantities of ApoB48 containing lipoprotein of the very low-density lipoprotein (VLDL) class while humans with atherosclerosis almost always have high level of cholesterol-rich LDL containing ApoB100." (PMID 29770337, 2018). "In contrast, such signaling via apoE enhances the M2-like properties of macrophages including phagocytosis and the secretion of anti-inflammatory cytokines that are recognized in the control of atherosclerosis progression and its regression." (PMID 29789495, 2018). "Favorable changes in lipid profile consisting in a decrease in plasma TC and LDL-C combined with an increased in plasma level of HDL-C and increased CYP27A1 activity, is a likely reason for which ApoE KO mice treated with RIF developed less atherosclerosis than their vehicle-treated littermates." (PMID 29191818, 2018). "Furthermore, temporal Cre-mediated gene repair of the Apoeh/h locus revealed a role for apoE in promoting the regression of atherosclerosis beyond reducing plasma lipid levels." (PMID 29789495, 2018). "Preliminary data from the authors’ laboratory support this possibility that could in part explain the observed reduced endothelial activation and atherosclerosis in hyperlipidemic mice that accumulate apoE in plasma." (PMID 29789495, 2018). "NE genetic–deficient mice (Apolipoprotein E−/−/NE−/− mice), bone marrow transplantation, and a specific NE inhibitor (GW311616A) were employed in this study to establish the causal role of NE in atherosclerosis." (PMID 29437605, 2018). "Thus, the ApoE−/− pigs established in this study are the first ApoE KO pig model with severe atherosclerosis phenotypes." (PMID 30305304, 2018). "Indeed a recent study also found increases in the PVAT content of M1 macrophages in the ApoE−/− mouse model of atherosclerosis, suggesting that macrophage polarization in the artery wall can drive vascular disease." (PMID 29479319, 2018). "We accept as limitation that although ApoE−/− mouse models could help us comprehend the pathogenesis of atherosclerosis, the characteristics of atherosclerosis are somewhat different between ApoE−/− mice and humans." (PMID 29922166, 2018).
atherosclerosis (continued). "Tg2576 mice develop little atherosclerosis and thus this study should be repeated in animals such as APOE knockout mice to assess the role of our HFD, which is rich in monounsaturated fatty acids and which increases substantially HDL cholesterol, on cerebrovascular disease." (PMID 30079520, 2018). "ApoE−/− mouse is a well-established animal model for studying atherosclerosis." (PMID 30533443, 2018). "Previous studies demonstrated accelerated atherosclerosis in ApoE KO mice exposed to CS." (PMID 29642385, 2018). "The importance of apolipoproteins in macrophage cholesterol efflux is evident as mice lacking ApoE specifically in macrophages are more susceptible to atherosclerosis." (PMID 29429624, 2018). "Further evidence of the protective effects of ECs in atherosclerosis comes from the demonstration that CB1 inhibition in ApoE−/− mice is able to promote the down-regulation of vascular angiotensin II type 1 receptor (AT1), which is responsible for NOXs activation when stimulated by angiotensin II." (PMID 30021985, 2018). "Thus, the present study was designed to further investigate the protective role of Rb1 against atherosclerosis using the well-defined classical ApoE-/- mouse atherosclerotic model." (PMID 30413028, 2018). "The lack of CD100 in ApoE-deficient mice was found to slow the progression of atherosclerosis, resulting in decreased lipid staining, macrophage infiltration and intimal neovascularization in the aortic plaques." (PMID 30324109, 2018). "Activation of NOD1 was shown to accelerate atherosclerosis in ApoE−/− mice." (PMID 29621153, 2018). "Indeed, it has been shown that fish oil increased aortic endothelial nitric oxide synthase expression and nitric oxide production in atherosclerosis-prone apolipoprotein E (−/−) mice." (PMID 29335432, 2018). "The possible explanations for these observations include a compensatory role of apoE through its multiple atheroprotective functions, including the formation of HDL-apoE particles that could provide protection from atherosclerosis." (PMID 30282955, 2018). "The present study was set up to investigate whether FH and apoE interaction could play a role in the induction and progression of atherosclerosis by macrophages." (PMID 30519244, 2018). "The relevance of this pathway for atherosclerosis development is highlighted by the observation that macrophage-targeted deletion of Fasn reduces atherosclerotic plaque formation and foam cell formation in ApoE−/− mice, probably through inactivation of LXRα." (PMID 28971272, 2018). "Novel rHDL formulations containing apoE could possibly present enhanced biological functions, leading to improved therapeutic efficacy against atherosclerosis." (PMID 30282955, 2018). "In humans, where the lack of ApoE is rare, the risk of atherosclerosis is strongly associated with three common apoE isoforms in the order of APOE4>APOE3>APOE2." (PMID 29439446, 2018).